RN7SL492P (RNA, 7SL, cytoplasmic 492, pseudogene)
Gene: Miscellaneous RNA gene on chromosome 4 (56,794,348 to 56,794,642, reverse strand). Ensembl gene ENSG00000240545.
Homologues: Orthologues: chimpanzee Metazoa_SRP (99% identical), macaque Metazoa_SRP (94% identical). Paralogues in human: RN7SL2 (87% identical), RN7SL1 (87% identical), RN7SL3 (86% identical), RN7SL543P (85% identical), Metazoa_SRP (84% identical), RN7SL679P (84% identical), Metazoa_SRP (83% identical), RN7SL296P (83% identical), RN7SL627P (83% identical), RN7SL300P (83% identical), RN7SL357P (83% identical), RN7SL620P (83% identical), and 703 more.